IL1B (interleukin 1 beta)
Diseases named in the same sentence as IL1B in open-access papers (continued):
Sharing a sentence is not in itself a finding about the gene and the disease.
osteoarthritis (continued). "Diacerein is an interleukin (IL)-1β inhibitor approved for osteoarthritis." (PMID 37454204, 2023). "In this study, an osteoarthritis cell model was prepared by treating primary chondrocytes with IL-1β; the effects of different naringenin concentrations on the secretion of inflammatory factors, matrix degradation, and apoptosis of chondrocytes were determined." (PMID 37953787, 2023). "Therefore, the study of IL-1β induced chondrocyte apoptosis, cartilage extracellular matrix degradation and inflammatory response is of great significance for the treatment of osteoarthritis." (PMID 37749650, 2023). "The inflammatory factor IL-1β is reported to be an important factor in initiating osteoarthritis." (PMID 37953787, 2023). "In addition, ASCs-derived EVs can promote the proliferation and migration of chondrocytes and slow the development of osteoarthritis by inhibiting IL-1β and inflammatory responses." (PMID 36710868, 2023). "In a rat osteoarthritis model, the activation of Bax and caspase 3/9 and the downregulation of Bcl-2, which were induced by IL-1β in SIRT3-overexpressing chondrocytes, were significantly reduced, indicating that SIRT3 protected chondrocytes from IL-1β-induced apoptosis." (PMID 37196115, 2023). "In addition, Morusin ameliorates IL-1β-Induced chondrocyte inflammation and osteoarthritis via NF-κB signal pathway." (PMID 37386395, 2023). "IL-1β led to the suppression of XT-I in cartilage tissue of late stage osteoarthritis patients." (PMID 36830996, 2023). "Furthermore, Dio has been reported to inhibit the expression of iNOS and COX-2 in IL-1β-induced human osteoarthritis chondrocytes." (PMID 37055831, 2023). "Diacerein is a drug prescribed for osteoarthritis in many countries due to its therapeutic properties, such as anti-inflammatory, anti-catabolic, and pro-anabolic actions during cartilage healing, by inhibiting the IL-1β signaling pathway." (PMID 38444710, 2023). "Moreover, IL-1β synergizes with other cytokines in the osteoarthritis progression, resulting in the metabolic imbalance of chondrocytes." (PMID 37953787, 2023). "The aqueous extract from Codium fragile decreased nitrite production, protein expression of iNOS, matrix metalloproteinase-13, a disintegrin and metalloproteinase with thrombospondin motifs (ADAMTS)-4, and ADAMTS-5 against IL-1β-induced osteoarthritis with the regulation of the MAPK/NF-κB signal." (PMID 37760047, 2023). "Regarding the anti-inflammatory effect of piperine in the literature, it was reported that this alkaloid reduced the expression of PTGS2, PGE2, and IL-1β in osteoarthritis models, reduced inflammation after UV-B irradiation, and reduced inflammation induced by cerebral ischemia-reperfusion." (PMID 36678600, 2023). "In vitro osteoarthritis model, IL-1β-induced chondrocyte injury model is widely used." (PMID 37749650, 2023). "IL-1β is the main inflammatory factor related to the occurrence and development of osteoarthritis." (PMID 36546928, 2022). "In addition, a study on osteoarthritis showed that the silencing of METTL3 suppressed IL-1β-induced inflammatory cytokines and the NF-κB signaling pathway in chondrocytes." (PMID 36293529, 2022). "A previous study demonstrated that dexamethasone had a chondroprotective effect, that is, it ameliorated arthritic pain and protected cartilage from damage in a rabbit osteoarthritis model via suppressing several pro-inflammatory gene markers, including il-1b, il-8, il-6, tnf-α, mmp-3, and mmp-13." (PMID 36429168, 2022). "Studies have shown that Mg2+ may affect osteoarthritis by inhibiting the expression of IL-1β, TNF-α, MMP13, and ADAMTS5 genes in macrophages, synoviocytes, and chondrocytes." (PMID 36546928, 2022). "Additionally, by blocking the NF-κB signaling pathway, Gyps can suppress the inflammatory response of osteoarthritis chondrocytes generated by IL-1β." (PMID 36157877, 2022).
osteoarthritis (continued). "In addition, inflammatory cytokines such as IL-1β can trigger YAP degradation through TAK1-mediated phosphorylation during osteoarthritis, thus linking the inflammation to the mechanical stress." (PMID 35968240, 2022). "Similarly, its sister miRNA miR-199a-3p targets cyclooxygenase-2 (Cox-2) to stabilize cartilage morphology by inhibiting interleukin-1β (IL-1β)-induced COX-2 expression in osteoarthritis chondrocytes." (PMID 36561044, 2022). "Similarly, IL-1b, IL-17, and TN-Fα worsen degenerative tendon disorders, whilst IL-1b, IL-6, and TNF-α have been linked to osteoarthritis development." (PMID 35159388, 2022). "As an inflammatory factor in osteoarthritis (OA), IL-1β plays a major role in OA cartilage destruction, which inhibits the proliferation of chondrocytes, induces apoptosis, causes the degradation of cartilage extracellular matrix, and aggravates cartilage erosion." (PMID 35968240, 2022). "In addition, the level of IL-1β, a major driver of osteoarthritis progression, is decreased in faster relaxing hydrogel." (PMID 36032700, 2022). "Also, miR-149 has been found to be downregulated in chondrocytes from patients with osteoarthritis and it correlates with increased expression of pro-inflammatory cytokines including IL-1β." (PMID 36712871, 2022). "Tan-I inhibits IL-1β-induced NF-ĸB activation in chondrocytes, a model for osteoarthritis." (PMID 35439976, 2022). "In addition, a certain degree of mechanical strain can also induce IL-1β expression in chondrocytes in osteoarthritis." (PMID 36575508, 2022). "In addition, circHIPK3 (circBase 000284), derived from mesenchymal stem cells, regulates miR-124-3p and MYH9 to prevent chondrocyte apoptosis and hypertrophy in the IL-1β-induced osteoarthritis model." (PMID 36700234, 2022). "However, the specific role and molecular mechanism of LMX1B in IL-1β-induced human osteoarthritis chondrocytes are poorly understood." (PMID 36133743, 2022). "IL1B is also involved in the pathogenesis of osteoarthritis." (PMID 36105284, 2022). "The expression levels of circCREBBP, screened by circular RNA sequencing during chondrogenic differentiation in adipose tissue-derived stem cells, and TGFβ2 were significantly increased in the cartilage of patients with osteoarthritis and IL-1β-induced chondrocytes." (PMID 36224344, 2022). "Importantly, our study showed significantly reduced production of oxidative markers when osteoarthritis chondrocytes were incubated with both FA and IL‐1β." (PMID 34078001, 2021). "FA prevents interleukin‐1β (IL‐1β)‐induced osteoarthritis chondrocyte toxicity, which suggests that FA may be a potential therapy." (PMID 34078001, 2021). "The reason might be that the previous study constructs a mouse model of traumatic osteoarthritis, while this study used IL-1β to induce OA in vitro." (PMID 33776787, 2021). "The role of IL-1b is highly discussed in the development and progression of osteoarthritis." (PMID 33477357, 2021). "Due to the role of IL-1β as an inflammatory mediator of osteoarthritis, the production of this cytokine in an ACS system could influence the potential therapeutic benefit." (PMID 34901249, 2021). "For instance, NR4A1 reactivation by its agonist cytosporone B could inhibit IL-1β induced chondrocyte inflammation, and injection of cytosporone B protected cartilage damage and alleviated osteoarthritis in rat osteoarthritis model." (PMID 34924813, 2021). "IL-1β treatment is therefore a well-established method to induce cartilage matrix degradation in a similar manner to that which occurs in vivo during inflammatory joint disease such as osteoarthritis." (PMID 34563724, 2021). "IL-1β not only has a role in osteoarthritis progression and cartilage degradation but also may contribute to fibrocartilage formation because it can induce Col1 expression through induction of the long noncoding RNA lncRNA-SAMD14-4." (PMID 35096790, 2021).
osteoarthritis (continued). "Interleukin‐1β (IL‐1β) is involved in osteoarthritis pathogenesis and mediates a series of toxic processes including the production of matrix metalloproteinase and inflammatory regulators which are suppressed by activation of silent information regulator 1 (SIRT1)." (PMID 34078001, 2021). "In vitro, it has been observed that harpagoside could inhibit interleukin (IL)-6 production from primary human osteoarthritis chondrocytes challenged with IL-1β." (PMID 34067240, 2021). "In summary, our study suggests that FA possesses powerful protective effects on IL‐1β‐induced osteoarthritis degeneration by preventing ECM degradation, suppressing inflammation responses, and inhibiting oxidative stress through regulation of the Sirt1/AMPK/PGC‐1α signaling pathway." (PMID 34078001, 2021). "The expression of miR-18a is induced by IL-1β and accelerates the progression of osteoarthritis." (PMID 34246297, 2021). "Therefore, an increase in PGE2 production is related to mPGES-1 and COX-2 derivatives from osteoarthritis chondrocytes stimulated by IL-1β." (PMID 33540695, 2021). "Our findings reveal that FA prevents IL‐1β‐induced osteoarthritis chondrocyte toxicity, which suggests that FA may be a potential therapy for osteoarthritis and warrants further investigation for its clinical application." (PMID 34078001, 2021). "IL-1β, a cytokine of the chemokine family, is involved in the pathogenesis of osteoarthritis." (PMID 34900977, 2021). "Besides suppressing macrophage IL-1β production, one study found that mannose treatment promoted proliferation, enhanced autophagy, and reduced apoptosis of IL-1β-treated rat chondrocytes, and therefore suppressed the progression of osteoarthritis (OA)." (PMID 34646279, 2021). "This positive correlation of IL-1β to IL-1Ra for the commercial method mirrors a similar correlation observed in joints with naturally occurring osteoarthritis, which may be due to a counter induction of IL-1Ra, in response to an increase in IL-1β." (PMID 34901249, 2021). "Thus, IL-1β induction in chondrocytes has been used as a routine method for generating osteoarthritis models in vitro." (PMID 34806937, 2021). "We next examined how FA affected IL‐1β‐induced cell injury in osteoarthritis chondrocytes." (PMID 34078001, 2021). "IL‐1β is one of the most important proinflammatory cytokines involved in the pathophysiology of osteoarthritis because it inhibits the synthesis of key components of cartilage—type II collagen and cartilage aggrecan—leading to increased cartilage degradation and aggravated inflammation." (PMID 33304230, 2020). "For these reasons, inhibitors that target IL-1RAcP or interfere with its ability to bind the IL-1β/IL-1R1 binary complex may represent a new paradigm in osteoarthritis treatment." (PMID 33614593, 2020). "During the progression of osteoarthritis, IL-1β levels are elevated, which activates the nuclear factor NF-κB pathways to induce the expression of matrix metalloproteinases (MMPs) in cultured chondrocytes, leading to ECM degradation, abnormal bone metabolism and inflammatory disease." (PMID 32854712, 2020). "In addition, there is evidence in experimental animals that sclerostin generated in response to TNF-α and IL-1β improves post-traumatic osteoarthritis by inhibiting the activity of proteolytic enzymes involved in cartilage degradation." (PMID 32947946, 2020). "However, haplotypes in the IL1B gene have previously been described in other inflammatory diseases such as osteoarthritis, RA, and SLE." (PMID 33330522, 2020). "Furthermore, moracin, a flavonoid from Mores alba root bark protects against IL-1β-induced osteoarthritis by reducing inflammatory factors (TNF-α, IL-6, and COX2) via attenuating the NF-κB pathway." (PMID 33371279, 2020). "Saponins of Achyranthes bidentata have protective effects on interleukin-1β- (IL-1β-) induced chondrocyte inflammation and apoptosis and may be a potential drug for the treatment of osteoarthritis." (PMID 33376732, 2020).
osteoarthritis (continued). "Interleukin-1 β (IL-1β) leads to osteoarthritis through NF-ĸB, IκBζ, and the Zn2+-ZIP8-MTF1 axis." (PMID 32079226, 2020). "Interleukin-1 receptor antagonist protein (IL-1ra or IRAP), is a potent anti-inflammatory protein that binds type IL-1 receptors and competitively inhibits IL-1α and IL-1β, both of which initiate a pro-inflammatory cascade in osteoarthritis through activation of NF-κB." (PMID 30895181, 2019). "Moreover, PRP-Exos and PRP-As both promoted osteoarthritis chondrocyte proliferation, and the cell viability was inhibited by IL-1β." (PMID 31888697, 2019). "Additionally, PVT1 promotes the production of inflammatory cytokines to aggravate the progression of IL-1β-stimulated osteoarthritis." (PMID 31304055, 2019). "The purpose of this study was to investigate the influence of moderate physical activity (MPA) on the expression of osteoarthritis (OA)-related (IL-1β, IL-6, TNF-α, MMP-13) and anti-inflammatory and chondroprotective (IL-4, IL-10, lubricin) biomarkers in the synovium of an OA-induced rat model." (PMID 30691048, 2019). "In the early osteoarthritis rat model, serum and synovial fluid confirmed that higher IL-1β could increase the expressions of AQPs, and decrease the cartilage matrix in both the chondrocytes and the cartilage." (PMID 31404098, 2019). "Inflammatory cytokines, including IL-1β, TNFα, and IL-6, play a key role in osteoarthritis, and IL-6 is considered to be the key cytokine; its effect is mainly based on promoting the formation of osteoclasts and bone resorption while synergism with IL-1β and TNFα." (PMID 31139654, 2019). "Inhibition of IL-1β-stimulated human osteoarthritis chondrocytes." (PMID 31817084, 2019). "It has been demonstrated that they can also decrease the adverse effect of IL-1β in osteoarthritis." (PMID 31316380, 2019). "Likewise upregulation of ANK2, in both the groups was predicted to inhibit MYBBP1, which was leading to development of osteoarthritis by NF-κB activation through activation of IL-1β similar to activation of TLR2 by upregulated fibronectin." (PMID 29731966, 2018). "Studies have shown that farrerol could inhibit the AKT/NF-κB signaling pathway in LPS-stimulated human gingival fibroblasts and IL-1β-stimulated human osteoarthritis chondrocytes, and this is consistent with our results." (PMID 29904013, 2018). "In support of this, previous studies have shown that KDACi increased IL-1β-induced miR-146a-5p expression in osteoarthritis fibroblast-like synoviocytes and upregulated basal as well as lipopolysaccharide (LPS)-stimulated miR-146a-5p expression in macrophages isolated from mice." (PMID 30260972, 2018). "During the development of osteoarthritis, IL-1β plays a key role in cartilage degradation." (PMID 29483929, 2018). "It has been reported that interleukin-1 beta (IL-1β), one of the main cytokines involved in the pathogenesis of osteoarthritis, can inhibit cell proliferation, reduce the synthesis of aggrecan and type II collagen, and increase the expression of MMP-13 in chondrocytes." (PMID 29483929, 2018). "Recent data from the worldwide CANTOS trial supports a role for IL-1β in osteoarthritis." (PMID 30459597, 2018). "In addition, IL-1β treatment of chondrocytes is an easy way to mimic inflammatory part of osteoarthritis in vitro, permitting to assess the interest of anti-arthritic molecules." (PMID 28744016, 2017). "Although, Schisandrae Fructus was recently reported to attenuate the interleukin (IL)-1β-induced inflammatory response in chondrocytes in vitro, its protective and therapeutic potential against osteoarthritis (OA) in an animal model remains unclear." (PMID 28507472, 2017). "Finally, IL-1β is considered the key molecule that triggers osteoarthritis (OA), while both NO and PGE2 play a role in the OA development." (PMID 27070563, 2016).
osteoarthritis (continued). "In addition to chondrocytes, macrophages contribute to inflammation and matrix degradation in osteoarthritis tissues, and inflammatory mediators such as IL-1β, TNF-α, IL-6, PGE2, and NO represent potential targets for osteoarthritis disease modification." (PMID 27411719, 2016). "Moreover, IL-1β and TNF-α induce activation of synovial fibroblasts and osteoclast cells that are associated with chronic inflammation and bone loss in osteoarthritis." (PMID 28036032, 2016). "In conclusion, our previous study has demonstrated that HA could suppress chondrocyte apoptosis in IL-1β-induced osteoarthritis model in a dose-dependent way." (PMID 25888442, 2015). "Thus, we suggest reported hedgehog induced matrix catabolism in osteoarthritis must be due to its interaction with pathological factors other than IL-1β." (PMID 26705100, 2015). "Furthermore, recent studies indicated that sulfonamide-based gallates effectively inhibited IL-1β induced osteoarthritis and exerted effects on cartilage growth." (PMID 26107568, 2015). "In the present study, the effects and mechanisms of mesenchymal stem cells (MSCs) on interleukin (IL)-1β-stimulated rat chondrocytes, as well as cartilage from a rat model of osteoarthritis (OA) induced by anterior cruciate ligament transection and medial meniscectomy were investigated." (PMID 25892273, 2015). "In our previous study, our results have shown that HA could suppress chondrocyte apoptosis in IL-1β-induced osteoarthritis model in a dose-dependent way." (PMID 25888442, 2015). "The objective of this study was to investigate the possible role of UDP-glucose dehydrogenase (UGDH) in osteoarthritis (OA) and uncover whether, furthermore how interleukin-1beta (IL-1β) affects UGDH gene expression." (PMID 25465897, 2014). "A recent study on in vitro cell cultures of human chondrocytes, has highlighted the role of IL-1β which plays a key role in the pathogenesis of osteoarthritis since determines significant changes in cytokine and chemokines genes expression involved in inflammation and matrix degradation." (PMID 25505929, 2014). "Inflammatory factors such as IL-1β are indicators of the existence and severity of osteoarthritis." (PMID 24819118, 2014). "This knowledge may be useful for developing novel therapies for blocking IL-1β stimulated cartilage breakdown in osteoarthritis." (PMID 23971790, 2013). "GS may slow down the destruction of cartilage in osteoarthritis (OA) by inhibiting the pro-inflammatory IL-1β." (PMID 22900984, 2012). "The absence of human IL-1β expression in the brain of the mice with osteoarthritis was confirmed by immunohistochemistry using an antibody raised specifically against a unique epitope of this cytokine that distinguishes it from murine IL-1β." (PMID 21899735, 2011). "In fact, recently reported ginsenosides showed anti-osteoarthritis activities through regulation of inflammation which drives the production of enzymes such as MMPs to break down the extracellular matrix of cartilage via regulation of pro-inflammatory cytokines such as IL-1β and TNF-α." (PMID 40507179, 2025). "The differential and cell-specific roles of TGF-β3 and IL-1β in the calcium homeostasis of osteoarthritic chondrocytes and hBM-MSCs during chondrogenesis may provide a new insight into future strategies for cartilage repair and osteoarthritis treatment." (PMID 40143007, 2025). "Moreover, IL-1β increases the expression of iNOS and COX-2 in cartilage, leading to the production of NO and PGE2 in chondrocytes, which are associated with the degradation of ECM and the onset of osteoarthritis." (PMID 38542192, 2024). "Therefore, inhibiting the expression of IL-1β could be used as a potential target in the treatment of osteoarthritis." (PMID 38741587, 2024).